ICAM1 (intercellular adhesion molecule 1)
Diseases named in the same sentence as ICAM1 in open-access papers (continued):
Sharing a sentence is not in itself a finding about the gene and the disease.
breast carcinoma (continued). "The expression levels of mRNA for ICAM1 were higher in breast cancer tissues compared with normal tissues." (PMID 33072116, 2020). "We have demonstrated that the adhesion of breast cancer cells and LECs, similar to the adhesion of colon cancer cells and LECs, is mandatory for intravasation and depends on ICAM-1 in LECs." (PMID 32365473, 2020). "More importantly, compared with other subtypes of breast cancer, the expression of ICAM1 in TNBC was significantly increased." (PMID 33072116, 2020). "The specific recognizing and killing of ICAM1-positive breast cancer cells by ICAM1-specific CAR-T cells were evaluated using 51Cr-release cytotoxic assay." (PMID 33072116, 2020). "In order to better verify the ability of mG2-scFv to bind to endogenous ICAM1 proteins in different breast cancer cell lines, target cells were examined by IF using mG2-scFv-Fc as the primary antibody." (PMID 33072116, 2020). "MDA-MB-231 and MDA-MB-468 exhibited a significant increase in Intercellular adhesion molecule-1 expression compared with various other subtypes of breast cancers and normal epithelium cells." (PMID 33072116, 2020). "In breast cancer cells, ICAM-1 activation was lower after moderate-intensity electrical stimulation in vitro." (PMID 31936342, 2020). "To explore the relationship of AF1q with ICAM-1 in breast cancer, we used 1,222 RNA-seq data of 1,092 breast cancer cases from TCGA database." (PMID 31297450, 2019). "Another group demonstrated that purified native OPN induces NF-κB activation and NF-κB-dependent ICAM-1 expression in breast cancer cells." (PMID 31731625, 2019). "To demonstrate that the AF1q expression was involved in ICAM-1 gene expression in breast cancer, we first experimentally overexpressed or suppressed AF1q expression in MDA-MB-231LN." (PMID 31297450, 2019). "The attachment between breast cancer cell monolayer and T cells was significantly reduced by AF1q-induced ICAM-1 attenuation, while enhanced ICAM-i expression by AF1q suppression increased the attachment." (PMID 31297450, 2019). "This study investigated the role of AF1q-attenuated ICAM-1 in progression and metastasis of breast cancer." (PMID 31297450, 2019). "The attachment between T cells and breast cancer cell monolayer was significantly reduced by pretreatment with a blocking antibody to ICAM-1." (PMID 31297450, 2019). "ICAM1 is a surface protein, mainly detectable in endothelial cells, but also expressed in human breast cancer cells." (PMID 29343717, 2018). "Taken together, our findings show that ICAM1 is expressed in aggressive subtypes of breast cancer and its expression is inducible by well-known proinflammatory cytokines." (PMID 30082828, 2018). "As such, we investigated the ability of metformin to alter the expression of ICAM1 in breast cancer cells using immunofluorescence and flow cytometry." (PMID 30469399, 2018). "Surprisingly, CCL2 has also been reported to negatively regulate ICAM1 expression and breast cancer metastasis." (PMID 30585203, 2018). "Taken together, our findings show that ICAM1 is upregulated in more aggressive subtypes of breast cancer and its expression is inducible by well-known proinflammatory cytokines, regardless of hormone receptor status of the tumor cells." (PMID 30082828, 2018). "For instance, the invasiveness of breast cancer cells has been positively correlated with the expression of ICAM-1." (PMID 29099772, 2017). "In this study, we found that ICAM-1 is involved in breast cancer metastasis and that its stability is regulated via the ERK pathway." (PMID 29137327, 2017). "In breast cancer, ICAM-1 expression is positively correlated with tumor progression and poor prognosis." (PMID 28903329, 2017).
breast carcinoma (continued). "Therefore, to investigate whether ICAM-1 stability is associated with the mesenchymal movement and invasiveness of metastatic breast cancer cells, we assessed the migratory and invasive characteristics of metastatic and non-metastatic breast cancer cells by analyzing EMT marker expression." (PMID 29137327, 2017). "ICAM-1 is involved in anchorage-independent growth and migration activity, and its suppression inhibits human breast cancer cell invasion." (PMID 28665963, 2017). "In the present study, we observed high ICAM-1 expression in advanced or metastatic breast cancer cells and found that ICAM-1 regulated EMT." (PMID 29137327, 2017). "In metastatic breast cancer cells co-expressing ICAM-1 and FBXO4, the level of ICAM-1 was significantly higher than that in cells overexpressing only FBXO4." (PMID 29137327, 2017). "Increased ICAM-1 expression increased metastatic progression potential in the luminal subtype of breast cancer compared with that in normal epithelial tissues." (PMID 29137327, 2017). "ICAM-1 level was higher in metastatic breast cancer tissue and lymph nodes than in normal breast cancer." (PMID 29137327, 2017). "Medullary breast carcinomas are defined in part by a florid lymphocytic infiltrate and showed a higher expression of ICAM-1 on intratumoral blood vessels than ductal breast carcinomas of no special type." (PMID 28066431, 2016). "In a different study, CCL2 induced the expression of the intercellular adhesion molecule ICAM-1 on human lymphatic endothelial cells and thereby facilitated the attachment of breast cancer cells to lymphatic endothelial cells." (PMID 25950608, 2015). "MUC1 has also been implicated in cytoskeletal reorganization and cell motility through Src-CrkL-Rac1/Cdc42 signaling cascade following ICAM-1/MUC1 interaction in breast cancer cells." (PMID 24504508, 2014). "In breast carcinoma, neutrophils were shown to cluster tumoral ICAM-1 and phosphorylate FAK (focal adhesion kinase) and paxillin via src, as well as p38-MAPK via Rho-GTPase." (PMID 23423155, 2013). "Pretreatment with ICAM-1 antibody or transfection with antisense ICAM-1 has been reported to reduce the migration of breast cancer cells." (PMID 24205072, 2013). "Studies have shown that the level of ICAM-1 protein expression on the cell surface positively correlated with metastatic potential of several breast cancer cell lines." (PMID 23874773, 2013). "Interaction of ICAM-1 on vascular or lymphatic endothelial cells has been found to promote the adhesion of lung cancer and breast cancer cells." (PMID 23098564, 2012). "Elevated levels of the intercellular adhesion molecule-1 (ICAM-1) and vascular cell adhesion molecule-1 (VCAM-1) are found in stage IV breast cancer patients and are associated with worse prognosis." (PMID 23113882, 2012). "This is significant because ICAM-1 is expressed throughout the migratory tract of a metastasizing breast cancer cell." (PMID 21798038, 2011). "ICAM-1 is expressed throughout the migratory track of a metastasizing breast cancer cell and its role in leukocyte extravasation is well characterized." (PMID 21798038, 2011). "Anti-metastatic effects of curcumin have also been demonstrated in the MDA-MB-231 breast cancer cell line, resulting in decreased expression of matrix metalloproteinases, ICAM-1 and chemokine receptor 4 (CXCR4) and suppressed cell migration and invasion." (PMID 21299897, 2011). "We were the first to report binding between MUC1 and Intercellular adhesion molecule-1 (ICAM-1), which is expressed on stromal and endothelial cells throughout the migratory tract of a metastasizing breast cancer cell." (PMID 21798038, 2011). "We also showed that OPN regulates cross-talk between NF-κB and AP-1 that leads to ICAM-1 expression in breast cancer cells." (PMID 20459645, 2010). "This study highlights the potential role of OPN to induce ICAM-1 expression through mTOR/p70S6 kinase pathway in breast cancer cells." (PMID 20459645, 2010).
breast carcinoma (continued). "Here, we provide the experimental evidence indicating that OPN induces ICAM-1 expression in breast cancer, MCF-7 cells." (PMID 20459645, 2010). "Breast cancer is one of the most debilitating diseases and earlier reports have shown that ICAM-1 plays important role in regulating invasion, tumor growth and metastasis in breast cancer." (PMID 20459645, 2010). "Notably, a study of resected primary human breast carcinomas revealed that the density of ICAM-1-expressing HEVs predicted both the extent of T and B cell infiltration and clinical outcomes in breast cancer." (PMID 39911389, 2025). "In addition, ICAM-1 expression on breast cancer cells in mice facilitates interactions with neutrophils that suppress lung metastasis, independent of cytotoxic T cell activity." (PMID 39911389, 2025). "Moreover, breast-cancer-specific immunoliposomes (intercellular adhesion molecule-1 [ICAM-1]-liposomes) promote clinical effectiveness by delivering siRNA." (PMID 38167116, 2024). "Additionally, the concentrations of MMP-9 and ICAM-1 were measured in the MDA-MB-231 breast cancer cells after 24 h of incubation with Les-6287, as well as doxorubicin." (PMID 39199694, 2024). "The findings of this work offer a foundation for the aberrant expression of ICAM-1 and its associated roles in TNBC subtypes of breast cancer; nevertheless, additional experimental validation is required to determine the precise function and intrinsic mechanism of this protein." (PMID 38799250, 2024). "Interestingly, ICAM-1 downregulation on breast cancer cells is a key escape mechanism from trastuzumab-triggered NK-mediated cytotoxicity, hampering the ability of these cells to establish productive ISs." (PMID 39596815, 2024). "However, the role of ICAM-1 in the regulation of growth, metastasis, and clinical prognosis of the specific molecular subtypes of breast cancer, triple-negative breast cancer (TNBC), remains to be elucidated." (PMID 38799250, 2024). "To validate the relationship between neutrophils and ICAM1 in tumor cells, we conducted immunofluorescence staining and immunohistochemistry on TNBC tissue sections from 4T1 tumor-bearing mice and breast cancer patients, revealing a clear spatial interaction between tumor ICAM1 and neutrophils." (PMID 38907234, 2024). "The findings demonstrated that the ICAM-1 high expression group’s breast cancer tissues had greater stromal, immunological, and overall ESTIMATE scores than the low expression group’s, indicating a considerably higher rate of immune cell infiltration in the high expression group." (PMID 38799250, 2024). "In comparison to other breast cancer subtypes, the ICAM-1 AUC was 70.9% in TNBC." (PMID 38799250, 2024). "In different types of breast cancer, ICAM-1 is highly correlated with TNBC, which can promote the occurrence and development of breast cancer and distant metastasis, and may be related to prognosis, immunotherapy, and drug resistance." (PMID 38799250, 2024). "In the breast cancer cohort, the ICAM-1 area under the curve (AUC) was 57.8%." (PMID 38799250, 2024). "Consistent with previous studies, our study found that ICAM1 could promote breast cancer cells local invasion." (PMID 36803413, 2023). "This process is dependent on ICAM-1 on breast cancer cells and β2-integrins on neutrophils." (PMID 37108425, 2023). "ICAM1 expression levels are higher in the TNBC subtype than in other breast cancer types." (PMID 37671167, 2023). "Low ICAM-1 expression levels on breast cancer cells made them resistant to αβ T-cell killing." (PMID 37139603, 2023). "Increasing evidence shows that FBXO proteins are involved in tumor development as either pro- or anti-oncogenic factors; for example, FBXO4 inhibits breast cancer development by interacting with intercellular adhesion molecule-1 (ICAM-1), promoting its ubiquitination, and decreasing its stability." (PMID 37348029, 2023).
breast carcinoma (continued). "ICAM1 downregulation upon GD3-synthase overexpression in ER-breast cancer but not in ER + cell line (MCF-7) suggested an association of estrogen receptor in GD2 mediated tumorigenesis." (PMID 38089042, 2023). "This analysis indicates that the predicted PTB-related genes including ICAM1, CRHBP, PLAGL1, EGR2, CNTLN, and DKK1 play an important role in preforming biological activities associated with PTB, infant disease, and possibly breast cancer, due to the gestational age-induced." (PMID 36788602, 2023). "Serum levels of both biomarkers, ICAM-1 and PECAM-1 were significantly higher in patients after breast cancer treatment and could be associated with cognitive dysfunction, depression, and vestibulocerebellar ataxia." (PMID 35366289, 2022). "Previously, it was demonstrated that ICAM-1 could be employed as a prognostic biomarker in breast cancer patients." (PMID 35366289, 2022). "Thus, neutrophils accumulated in the spleens of tumor-bearing donor mice can readily enter the lung vasculature and use ICAM-1 on E0771 cells entrapped inside this vasculature for the elimination of the breast cancer targets." (PMID 35911772, 2022). "We report that neither the growth of this breast cancer line in primary orthotopic tumors nor its susceptibility to killing by CTLs is affected by ICAM-1 deletion." (PMID 35911772, 2022). "In the present study, in order to investigate the role of ICAM-1 in a breast cancer model of tumor growth, progression, and metastasis, we used both spontaneous and experimental metastasis models based on the metastatic, C57BL/6 derived, medullary breast adenocarcinoma E0771 cell line." (PMID 35911772, 2022). "Furthermore, the ability of these donor spleen neutrophils to eliminate E0771 lung metastasis was entirely dependent on the presence of ICAM-1 on the breast cancer cells (second vs. fifth bar)." (PMID 35911772, 2022). "ICAM-1 is expressed by human and murine breast cancer cells." (PMID 35911772, 2022). "Additional studies have compared the expression of other adhesion molecules in radioresistant and radiosensitive breast cancer cell lines and found that the resistant cancer cells have increased expression of intercellular adhesion molecule-1 (ICAM-1) and vascular cell adhesion molecule-1 (VCAM-1)." (PMID 35992826, 2022). "Similarly, NF-κB activation by TNF-α increases ICAM-1 expression in breast cancer, which is upregulated to promote metastasis and is associated with more aggressive subtypes." (PMID 34404457, 2021). "In breast cancer, synergism between CD8+ T cells and γδ T cells has been described in the eradication of tumor cells including CSCs: γδ T cells induced upregulation of MHC class I and CD54/ICAM-1 on CSCs, enhancing their susceptibility to CD8+ T cells." (PMID 33806296, 2021). "These promising results warrant further development of GT DcNPs targeting ICAM-1-positive breast cancer (and maybe other cancers) to improve clinical outcomes with higher margin of safety." (PMID 35056985, 2021). "More human breast cancer cell lines have been previously investigated for ICAM-1 expression (e.g., MCF-7 which is HR+/HER2− has low ICAM-1 expression among other cell lines tested), and it was found that the cancer invasiveness was positively correlated with the ICAM-1 expression level." (PMID 35056985, 2021). "The capacity of infiltration of breast cancer cells is related to ICAM-1 expression." (PMID 34299272, 2021). "We hypothesized that LE administration could suppress breast cancer progression by decreasing ICAM-1 expression while increasing E-Cadherin expression." (PMID 34691393, 2021). "To investigate whether breast cancer cells express ICAM-1, which would be used for targeting drug combinations in GT DcNPs, we evaluated a LFA1-P peptide mimic of ICAM-1 ligand: LFA-1 peptide immobilized on GT DcNPs." (PMID 35056985, 2021).
breast carcinoma (continued). "A previous study reported that down-regulation of miR-486-5p could suppress tumor metastasis by regulating metastatic mediator of ICAM-1 in breast cancer." (PMID 33935718, 2021). "Studies have demonstrated that the expression of ICAM1 in TNBC is higher than that in other types of breast cancer, and it has been speculated that ICAM1 can serve as a therapy target for TNBC." (PMID 33072116, 2020). "Indeed, when comparing the human breast cancer cell line MDA-MB435 (ICAM-1+ and MMP-9−) to transfected MDA-MB435 (ICAM-1+ and MMP-9+), the transfected cells had a higher concentration of soluble ICAM-1 in the supernatant and were more resistant to NK cells." (PMID 32063906, 2020). "It is noteworthy that ICAM1 expression could be induced by proinflammatory cytokines, in breast cancer cell lines and normal breast epithelial cells." (PMID 33072116, 2020). "Reduced expression of ICAM-1 could play a role in the suppression of tumor progression in many cancer cells, such as breast cancer, gastric cancer, lung cancer and colorectal cancer." (PMID 32195055, 2020). "Furthermore, ICAM1 expression correlated with the metastatic capacity of five human breast cancer cell lines, suggesting its key role in invasion and dissemination." (PMID 30657059, 2019). "Because ICAM-1 is associated with the recognition of T cells, we wanted to determine whether ICAM-1 dysregulation by AF1q is essential for the T cell attachment to breast cancer cells." (PMID 31297450, 2019). "Decreased ICAM-1 expression affected the attachment of T cells to a breast cancer cell monolayer." (PMID 31297450, 2019). "In vitro targeting of ICAM1 reduced breast cancer cell invasion and metastasis." (PMID 30657059, 2019). "It has also been demonstrated by exploiting ICAM1 overexpression in breast cancer cells, that ICAM1 may serve as an effective nanomedicine target by delivering siRNA to TNBC cells and inhibiting cancer progression." (PMID 30082828, 2018). "ICAM1 may be an attractive molecular target for TNBC, but further investigations elucidating the role of ICAM1 in targeted therapies have to take into consideration selective subtypes of breast cancer." (PMID 30082828, 2018). "In this study, we have evaluated the ICAM1 expression in breast cancer." (PMID 30082828, 2018). "Since we observed a selective expression pattern of ICAM1 in our study, we wanted to investigate whether expression of ICAM1 in breast cancer cell lines could be induced by cytokines." (PMID 30082828, 2018). "Furthermore, cell from normal mammary epithelium and breast cancer cell lines expressed ICAM1 upon stimulation with the proinflammatory cytokines TNFα, IL1β and IFNγ." (PMID 30082828, 2018). "The ICAM-1 monoclonal antibody UV3, an anti–human CD54 antibody, has also been found to inhibit the growth of multiple myeloma, lymphoma, uveal melanoma, breast cancer, prostate cancer, non–small cell lung cancer, and pancreatic cancer in severe combined immunodeficiency mice." (PMID 29228586, 2017). "Also, it has been suggested that an ICAM-1–ICAM-1 homophilic interaction between breast cancer cells and mesenchymal stem cells in bone marrow mediates the metastatic expansion of cancer cells, displacing hematopoietic stem cells from their niche." (PMID 29099772, 2017). "Indeed we demonstrate that membrane-bound ICAM-1 is overexpressed in CAF isolated from head and neck, lung and breast cancers, which strongly suggests that in such cells ICAM-1 plays a role consistent with the functions we unveiled in vitro." (PMID 27901489, 2017). "Besides, we confirmed that high expression of ICAM-1 was observed in human metastatic breast cancer tissue whereas expression of FBXO4 was decreased particularly." (PMID 29137327, 2017). "Therefore, as a prerequisite for lymph endothelial barrier breaching the ICAM-1-dependent adhesion between LECs and breast cancer cells seems to be a rather general mechanism, which can be manipulated in various ways." (PMID 26513020, 2015).